DACH1 (dachshund family transcription factor 1)
Description:
Transcription factor that is involved in regulation of organogenesis. Seems to be a regulator of SIX1, SIX6 and probably SIX5. Corepression of precursor cell proliferation in myoblasts by SIX1 is switched to coactivation through recruitment of EYA3 to the SIX1-DACH1 complex. Transcriptional activation also seems to involve association of CREBBP. Seems to act as a corepressor of SIX6 in regulating proliferation by directly repressing cyclin-dependent kinase inhibitors, including the p27Kip1 promoter (By similarity). Inhibits TGF-beta signaling through interaction with SMAD4 and NCOR1. Binds to chromatin DNA via its DACHbox-N domain (By similarity).
Synonyms: DACH
Tractability: PROTAC: ubiquitination databases record sites on it.
Gene: Protein-coding gene on chromosome 13 (71,437,966 to 71,867,204, reverse strand). Ensembl gene ENSG00000276644.
Subcellular location: Nucleus
Subcellular location (Human Protein Atlas): Nuclear speckles; Nucleoplasm
Gene Ontology:
Molecular function: DNA-binding transcription repressor activity, RNA polymerase II-specific; protein binding; RNA polymerase II cis-regulatory region sequence-specific DNA binding; RNA polymerase II transcription regulatory region sequence-specific DNA binding; DNA-binding transcription factor activity, RNA polymerase II-specific; DNA-binding transcription factor activity
Biological process: negative regulation of cell migration; negative regulation of DNA biosynthetic process; negative regulation of DNA-templated transcription; negative regulation of transcription by RNA polymerase II; regulation of transcription by RNA polymerase II; regulation of nuclear cell cycle DNA replication
Cellular component: nuclear speck; nucleoplasm; nucleus; transcription regulator complex; cytoplasm
Genetic constraint (gnomAD): Loss-of-function variants: 11 observed, 49.04 expected, observed/expected ratio (o/e) 0.22, 90% interval 0.14 to 0.37. The upper end of that interval is the gene's LOEUF score, 0.37, which puts it in group 1 of 6, group 1 being the genes least tolerant of losing a copy. Missense variants: 703 observed, 790.14 expected, observed/expected ratio (o/e) 0.89, 90% interval 0.83 to 0.95. Synonymous variants: 342 observed, 303.98 expected, observed/expected ratio (o/e) 1.13, 90% interval 1.03 to 1.23.
Homologues: Orthologues: chimpanzee DACH1 (99% identical), macaque DACH1 (99% identical), pig DACH1 (98% identical), dog DACH1 (96% identical), guinea pig DACH1 (96% identical), mouse Dach1 (95% identical), rat Dach1 (95% identical), rabbit DACH1 (81% identical), tropical clawed frog dach1 (78% identical), Drosophila melanogaster dac (33% identical), Caenorhabditis elegans dac-1 (21% identical). Paralogues in human: DACH2 (46% identical).
Diseases named in the same sentence as DACH1 in open-access papers:
DACH1 is named in the same sentence as 114 diseases in open-access papers, as found by Europe PMC text mining. Sharing a sentence is not in itself a finding about the gene and the disease. The quoted sentences say what the papers report.
breast carcinoma (44 papers, 2012 to 2024). "DACH1 is a well-established suppressor of breast cancer, and the loss of DACH1 is associated with malignant biological properties of breast cancer." (PMID 38093319, 2023). "Previous study has implicated that DACH1 enriched in luminal A breast cancer and its expression fluctuated in direct proportion to the level of luminal-like marker FOXA113." (PMID 28659634, 2017). "In this study, we showed that in breast cancer cells the expression of DACH1 was specifically associated with cell adhesion." (PMID 25775416, 2015). "Previously, we showed that DACH1 was lost in triple negative breast cancers associated with stem cell property, and high expression of DACH1 predicted a 40-month survival advantage in all types of breast cancer." (PMID 25322986, 2014). "Clinical studies have demonstrated a correlation between poor prognosis and reduced expression of the cell-fate determination factor DACH1 in breast cancer, and loss of DACH1 expression has been observed in prostate and endometrial cancer." (PMID 23798621, 2013). "We observed that decreased expression of DACH1 in TNBC breast cancer patients was associated with poor overall survival and progression free survival and that inhibition of DACH1 significantly increased acquisition of a stem-like ALDHhiCD44+ phenotype in TNBC cells." (PMID 38581619, 2024). "We anticipate that DACH1 mutations result in loss of transcriptional repression of these regulators resulting in uncontrolled cell cycle progression in endometrial cancer, similar to DACH1’s control of the cell cycle via cyclin D1 in breast cancer." (PMID 33378353, 2020). "Our results indicated that EYA2 was inversely associated with DACH1 in breast cancer." (PMID 30761270, 2019). "It has previously been observed that reduced DACH1 expression occurs in invasive cancer compared to normal breast epithelium confirmed by our findings where DACH1 expression showed an inverse association with mitosis and cyclin D1 expression in breast cancer patient samples." (PMID 24392136, 2014). "The current study aims to characterise the association of DACH1 with other cancer relevant biomarkers in the luminal subtype of breast cancer, with the emphasis being in determining its possible role as a clinical classifier of disease outcome and as a prognostic biomarker." (PMID 24392136, 2014). "Association of DACH1 protein with other breast cancer biomarkers." (PMID 24392136, 2014). "Furthermore, exposure of tbLCM or loss of function of DACH1 in breast cancer cells significantly increased expression of KLF4, CD44 and Vimentin, indicating that one or more secreted factors in the LCM derived from TNBC tumor-bearing mice influences stemness/plasticity in breast cancer cells." (PMID 38581619, 2024). "Taken together these results suggested a link between FGF2 and Dach1 in influencing stemness/plasticity in breast cancer cells." (PMID 38581619, 2024). "We observed that several genes including PTCH1, ATXN1, DLL4, SOX2 and DACH1 were differentially regulated in tbLCM-treated breast cancer cells as compared to those treated with tnLCM or BM control." (PMID 38581619, 2024). "Taken together, these results further support the concept that soluble factors in the primed lung microenvironment influence stemness/plasticity in TN breast cancer cells through suppression of DACH1 expression." (PMID 38581619, 2024).
breast carcinoma (continued). "Analysis of breast cancer patient data through TCGA revealed that DACH1 expression is significantly downregulated in TNBC as compared to normal breast tissue (p≤0.01 × 10− 11)." (PMID 38581619, 2024). "This study highlights the complex interplay between FGF2, DACH1 and the lung microenvironment in influencing the stemness and metastatic behaviour of breast cancer cells." (PMID 38581619, 2024). "DACH1, a putative tumor suppressor, is involved in the oncogenesis of various cancers, such as breast cancer (BC), prostate cancer, and so on." (PMID 36750914, 2023). "DACH1 hyper-methylation results in epigenetic silencing in various cancers, including esophageal and breast cancers." (PMID 36750914, 2023). "It is noteworthy that the combined assessment of S100A8/A9 and DACH1 provides a more precise means of predicting outcomes for breast cancer patients, potentially serving as a promising biomarker for risk classification and prognosis prediction." (PMID 38093319, 2023). "The combination of S100A8/A9 and DACH1 predicted the overall survival of breast cancer patients more preciously." (PMID 38093319, 2023). "In vitro experiments indicated that DACH1 overexpression reduced the production of S100A8 in breast cancer cells." (PMID 38093319, 2023). "DACH1 is a human homolog of the Dachshund gene, and it has been reported to there is an abnormal expression in a variety of carcinomas, such as breast cancer, gastric cancer, renal Cell Carcinoma and others." (PMID 34772908, 2021). "The expression of DACH1 in different breast cancer cell lines was examined by western blot analysis." (PMID 34772908, 2021). "Our work showed that DACH1 exerted an important effect on inhibiting the metastasis of breast cancer cells, and further studies would provide a novel strategy for treating breast cancer invasion and metastasis in humans." (PMID 34772908, 2021). "In this study, DACH1 inhibited the invasion and metastasis of breast cancer cells by decreasing MMP9 expression." (PMID 34772908, 2021). "Further investigation in TCGA database indicated that DACH1 expression was lower in breast cancers especially basal-like subtype." (PMID 32550045, 2020). "For breast cancer, decreased DACH1 led to accelerated cell cycle, enhanced stemness, invasion, and metastasis." (PMID 32550045, 2020). "Most well-studied in breast carcinoma, DACH1 is expressed in normal mammary epithelium with significantly reduced expression found in mastopathy, ductal carcinoma, and lobular carcinoma in situ." (PMID 33378353, 2020). "Consisting with our study, nuclear DACH1 expression was observed in normal and Luminal breast cancer tissues." (PMID 32550045, 2020). "Survival analyses demonstrated that DACH1 was a favorable factor while EYA2 and SIX1 were risk factors for breast cancer patients." (PMID 32550045, 2020). "Several groups attempted to address the prognostic and therapeutic response value of DACH1 in breast cancer." (PMID 32550045, 2020). "Based on the expression profiles from TCGA database, we compared the DACH1 level between normal breast tissues and breast cancer samples." (PMID 32550045, 2020). "DACH1 plays a critical role in cell cycle control and acts as a tumor suppressor gene in breast cancer." (PMID 33378353, 2020). "DACH1 expression is dysregulated in human breast cancer and acts as an endogenous inhibitor of ESR1 function." (PMID 32117782, 2019). "DACH1 was reported to be an anti-tumor protein in breast cancer, while EYA2 served as a tumor-driving molecule in breast carcinoma." (PMID 30761270, 2019). "In progressive breast cancer tissues, the Dach1 signal is lost, and decreases in E-cadherin expression, loss of intercellular adhesion and loss of epithelial morphology have been observed accompanying increases in metastasis and infiltration." (PMID 31405829, 2019). "Patients with relatively low DACH1 expression showed lower 5-year overall survival among lung adenocarcinoma, endometrial cancer and luminal breast cancer." (PMID 30261897, 2018).
breast carcinoma (continued). "DACH1 had been proved to be negatively correlated with the development and progression of breast cancer and prostate cancer." (PMID 29636079, 2018). "MiRNA-194 and miRNA-217 are known to target DACH1 in pancreatic ductal adenocarcinoma and breast cancer, respectively." (PMID 30261897, 2018). "Breast cancer patients with reduced DACH1 expression had three years shorter time to death in comparison to those with normal DACH1 levels." (PMID 28659634, 2017). "In this respect, research has also shown that the decreasing of DACH1 is tightly correlated with poor prognosis in basal-like breast cancer, suggesting the role of DACH1 as a potential predictor of survival in breast cancer patients." (PMID 27793013, 2017). "For example, we have used anti-Flag to map the location of DACH1, a protein with roles in breast cancers, in breast cancer cell line MDA- MB-231 with stably expressed Flag-DACH1." (PMID 29796335, 2017). "Herein, we utilized immunohistochemistry (IHC) staining and public microarray data analysis showing that DACH1 was higher in normal breast, low-grade and luminal-type cancer in comparison with breast carcinoma, high-grade and basal-like tumors respectively." (PMID 28659634, 2017). "On the contrary, another key RDGN member DACH1 behaved as a tumor suppressor and reduced expression of DACH1 predicts poor survival performance of breast cancer patients." (PMID 28659634, 2017). "Breast cancer Met-1 cells were transducted with a DACH1 expression vector resulting in an ∼4.5-fold increase in DACH1 expression and subsequent reduction of CSC markers CD44, KLF4 and MYC as well as EMT markers including FN1 and VIM by mRNA analysis." (PMID 28659634, 2017). "Reduced expression of DACH1 tightly correlates with poor prognosis in breast cancer, as was first demonstrated in a tissue microarray analysis of over 2,100 samples, and was subsequently supported in an artificial neural network (ANN) approach." (PMID 27203207, 2016). "It has been indicated that DACH1 binds the endogenous IL-8 promoter to block breast cancer cellular migration in vitro and metastasis in vivo." (PMID 27203207, 2016). "Among the three different human breast cancer cell lines that were investigated, high level of DACH1 expression was displayed by MCF-7 and T47D cells, which also displayed epithelioid morphology and prominent cell–cell contact." (PMID 25775416, 2015). "Using bioinformatics analysis, we found that miR-217 targeted multiple cancer-related genes that have been reported to have a close link with cancers, such as KRAS (pancreatic cancer), E2F3 (hepatocellular carcinoma), and DACH1 (breast cancer)." (PMID 26016795, 2015). "In this study, significant correlation between the expression of DACH1 and the morphology of breast cancer cells was observed." (PMID 25775416, 2015). "Several lines of evidence have indicated the potential value of DACH1 as a prognostic factor in breast cancer for its strong connection between the poor clinical outcome and lower expression of DACH1." (PMID 25940701, 2015). "Given that the regulation of mesenchymal markers is crucial to EMT,11, 13 the effect of DACH1 expression on the expression levels of another epithelial marker and two mesenchymal markers in breast cancer cells was investigated." (PMID 25775416, 2015). "It has been demonstrated that DACH1 antagonizes FOXM1 signaling through competitively binding to the conserved forkhead specific DNA sequence in breast cancer." (PMID 25788272, 2015). "Recently, Dr. Powe's study demonstrated that high expression of DACH1 predicted a better survival in luminal breast cancers subtype, further supporting the importance of DACH1 as a prognostic factor." (PMID 25788272, 2015).
breast carcinoma (continued). "In breast cancer, DACH1 has been shown to repress CXCL8 through blocking activation from AP1 and NF- kappaB binding sites and inhibit cyclin D1 transcription though AP-1/CREB." (PMID 25788272, 2015). "Surprisingly, DACH1 and E-cadherin were uniformly expressed at background levels in all breast cancer cell lines (MCF-7, T47D and ZR-75-30 cells) tested." (PMID 25775416, 2015). "We first reported that breast cancer patients with low DACH1 expression have a 40-month survival disadvantage." (PMID 25788272, 2015). "Specifically, DACH1 restrains the tumorigenesis as well as influences the malignant phenotype of carcinoma, mainly including breast cancer, renal cancer, lung, colorectal and prostate cancer." (PMID 25940701, 2015). "Dachshund homologue 1 (DACH1) expression is lost in invasive breast cancer with poor prognosis, and the role of DACH1 in regulating breast cancer metastasis is poorly understood." (PMID 25775416, 2015). "To extend our analysis of the role of DACH1 in cell motility, we used scratch wound-healing and transwell assays to demonstrate the migration and invasion capacity, respectively, of breast cancer cells." (PMID 25775416, 2015). "Analysis of tissue samples taken from human breast cancers showed a significant correlation between the expression of DACH1 and E-cadherin in SNAI1-positive breast cancer." (PMID 25775416, 2015). "To establish an interaction map with only DACH1 in luminal (ER-positive) breast cancer samples, we created a DACH1 interactome using the 100 best predictive genes." (PMID 24392136, 2014). "The effect of endocrine therapy on the ability of DACH1 to predict breast cancer specific survival was considered using Kaplan-Meier modelling." (PMID 24392136, 2014). "In summary, we have shown that DACH1 occurs in patients with ER+ breast cancers and predicts good prognosis." (PMID 24392136, 2014). "The deletion of DS domain abolished the repression of Cyclin D1 in breast cancer and the overexpression of DS domain alone substituted DACH1 to repress S phase entry in breast cancer cells." (PMID 25322986, 2014). "Specifically, Six1 and EYA1 upregulated cyclin D; In contrast, DACH1 acted as an antagonist of cyclin D1 in breast cancer." (PMID 25322986, 2014). "Recent breast cancer studies have shown that DACH1 can directly influence the gene expression of stem cells, causing them to under-express CD24." (PMID 24392136, 2014). "Chromatin immunoprecipitation with a flag antibody and PCR amplified human cyclin D1 promoter sequence supported a model that DACH1 was recruited into cyclin D1 promoter context at AP-1 site, as previously observed in human breast cancer." (PMID 25322986, 2014). "In this study, we have used an artificial neural network (ANN) approach to identify DACH1 as a candidate luminal marker and its role in predicting clinical outcome in breast cancer is assessed." (PMID 24392136, 2014). "DACH1 inhibits breast cancer tumor metastasis and reduces breast cancer stem cell expansion via Sox2/Nanog." (PMID 23798621, 2013). "The relative abundance of DACH1 and p21CIP1 were compared amongst the five distinct mRNA subtypes of human breast cancer." (PMID 23798621, 2013). "Taken together, this data suggested that activation of Fgf2 signaling may decreases DACH1 expression to promote metastatic colonization and stemness/plasticity in breast cancer cells." (PMID 38581619, 2024).